LEP (leptin)
Diseases named in the same sentence as LEP in open-access papers (continued):
Sharing a sentence is not in itself a finding about the gene and the disease.
Obesity (continued). "Impaired hypothalamic signaling has been implied to underlie leptin resistance in obesity." (PMID 33804250, 2021). "Also, these compounds minimally affect the body weight and metabolic disorders in genetically predisposed obesity, such as ob/ob and db/db mice, which lack leptin or the LEP-R." (PMID 34084149, 2021). "In the case of children with obesity and “breakfast skippers”, it has been established that they present some metabolic alterations (e.g., leptin gene mutation, reduction of carbohydrate utilisation) associated with a reduction in attention and verbal, non-verbal, and short-term memory." (PMID 33923639, 2021). "Since endogenous control genes in human adipose tissue were identified and the relevance to obesity and obesity-associated type 2 diabetes mellitus was found, it would be interesting to know if the patients classified in the high leptin group were also those with a higher BMI." (PMID 33804101, 2021). "In states of overweight/obesity leptin sensitivity might be impaired causing an increased production." (PMID 34876619, 2021). "Leptin deficiency can cause diet-induced obesity and metabolic dysregulation." (PMID 34552557, 2021). "Adipose tissue mass and leptin concentration are directly proportional; therefore hyper-leptinemia is linked to obesity.The increased leptin triggers an inflammatory response and promotes endothelial dysfunction by oxidative stress, which further more leads to atherosclerosis and thrombosis." (PMID 35539887, 2021). "Some leptin negative regulators are upregulated in response to endoplasmic reticulum stress rather than chronic leptin signalling, a situation that is also linked to obesity." (PMID 34502119, 2021). "Microglial inflammatory signaling may induce obesity by causing hypothalamic neuronal dysfunction, including the induction of neuronal insulin and leptin resistance." (PMID 34122343, 2021). "In addition to leptin, deregulation of the adipokine adiponectin has been implicated in driving tumor progression in several obesity-associated cancer types, including colon, liver, breast, renal, gastric, esophageal, pancreatic and endometrial cancer." (PMID 33987528, 2021). "So it seems that obesity has a positive correlation with LEP polymorphism." (PMID 34868961, 2021). "In the homozygous mutation subjects, a truncation of the receptor before the transmembrane domain completely abolishes leptin signaling, leading to a form of massive obesity similar to that seen with leptin deficiency, along with significant growth retardation and central hypothyroidism." (PMID 34390703, 2021). "Pre-clinical studies have also shown an aberrant microbiota in genetic (Ob/Ob mice deficient in leptin production) or diet-induced (Zucker fa/fa rat) obesity animal models, suggesting the role of obesity in the dysbiosis of the gut microbiota and risk of colon cancer." (PMID 34680308, 2021). "LEP, which encodes leptin, is well-known because of its significant role in obesity." (PMID 34054919, 2021). "Thus, the orexigenic effect of CB1has been associated with the function of the peripheral neuronal system, regulated by leptin and associated with the development of overweight and obesity." (PMID 33530406, 2021). "It follows, therefore, that reducing leptin susceptibility to leptin in individuals with a mutated 385A allele may lead to an increased risk of developing obesity with the related metabolic complications." (PMID 33530406, 2021). "Additionally, elevated serum leptin is known to impact β cell function in obesity, and in keeping with this, serum leptin is associated with β cell function in IIH (HOMA-%B, P = 0.029, r = 0.33)." (PMID 33848268, 2021). "CHH patients may occasionally display a mild obese phenotype; however, patients affected by normosmic CHH and severe early-onset obesity harbor pathogenic variants in LEP (chr 7q31.3) and LEPR (chr1p31) genes." (PMID 34502334, 2021).
Obesity (continued). "Sleep deprivation may predispose to obesity by altering the activity of appetite-controlling hormones - leptin and ghrelin and by elevating the cortisol levels, both of which have been linked to an increase in energy intake and reduction in energy expenditure." (PMID 34781921, 2021). "Finally, in obesity conditions a large amount of leptin is secreted by adipocytes and this is associated with the inflammation state." (PMID 33920841, 2021). "However, we did not discuss the role of perivascular adipose tissue (PVAT)-derived leptin on the pathogenesis of atherosclerotic complications associated with diabetes and obesity, and this constitutes a limitation of this review." (PMID 34064112, 2021). "Obesity is also associated with decreased brown adipose tissue activity and attenuated metabolic responses to the hormone leptin, which, under normal conditions, promotes satiety and stimulates sympathetic outflow to brown adipose tissue to increase resting metabolic rate." (PMID 34208939, 2021). "Therefore, it is reasonable to propose that obesity-associated protein factors such as leptin, as well as other adipokines, are likely involved in the development of articular degenerative inflammatory diseases." (PMID 33673730, 2021). "Moreover, central resistance to leptin signalling is a hallmark of obesity in animal models and human subjects." (PMID 34156126, 2021). "Obesity is associated with leptin resistance despite increased leptin levels." (PMID 33668583, 2021). "However, it was soon discovered that administering leptin to obese individuals to reduce appetite was unsuccessful because obesity is associated with a resistance to leptin as a result of excessive adipose deposits and subsequent excessive leptin levels." (PMID 34066779, 2021). "Furthermore, obesity is associated with high levels of inflammatory cytokines, such as leptin, IL-6, and TNF-α, produced by adipocytes and immune cells infiltrating adipose tissue." (PMID 33343662, 2020). "Some of the genes associated with monogenetic severe obesity are: leptin (LEP), leptin receptor (LEPR), proopiomelanocortin (POMC), MC4R, preproconvertase 1 (PCSK1), single minded 1 (SIM1), brain-derived neurotrophic factor (BDNF), and tyrosine kinase receptor tropomycin-related kinase B (TrkB)." (PMID 32982666, 2020). "Humans with mutations of leptin or its receptor present the phenotype of obesity and infertility." (PMID 32183843, 2020). "In addition to the obesity-associated influence on macrophage behavior, the altered anti-tumor immune response observed in obesity has been proposed to be mediated by other mechanisms, some of which are linked to leptin." (PMID 33604295, 2020). "Because the level of plasma leptin is a biomarker for metabolic impairment, such as obesity and type 2 diabetes, it could also represent the risk of cardiovascular dysfunction." (PMID 33114326, 2020). "Hyperinsulinemia and obesity are therefore linked with high leptin and low adiponectin levels." (PMID 32911852, 2020). "Leptin is considered a biomarker associated with obesity and obesity-mediated diseases." (PMID 33374256, 2020). "CNS leptin and insulin resistance are linked to obesity and related metabolic disorders, and several studies suggest that ER stress may be causally associated with this dysregulation." (PMID 33092099, 2020). "In addition, as expected, the CAF group showed increased serum leptin levels reinforcing the well-established association between leptin resistance and obesity." (PMID 32033223, 2020). "Increased leptin concentrations are well associated with obesity and triglyceride storage." (PMID 33269023, 2020). "Furthermore, the Arc has been proposed as a potential region in which the leptin-melanocortin and renin-angiotensin-aldosterone systems interact to control sympathetic nerve activity, relevant to obesity-associated arterial hypertension." (PMID 32720895, 2020).
Obesity (continued). "Interestingly, using another obesity mouse model, leptin-deficient (ob/ob) mice, we also observed a significant decreased of MAIT cell frequency in both ileum and Epi-AT when compared with (ob/+) littermate controls." (PMID 32709874, 2020). "Especially, body fat percentage, leptin and insulin resistance are among other indicators of increased fat mass and might thus be associated with chronic low-grade inflammation in obesity." (PMID 33328935, 2020). "The ratio of adiponectin to leptin is a good indicator of adipose tissue dysfunction and an important indicator for estimating cardiac metabolic risk associated with obesity and metabolic syndrome; high adiponectin levels are associated with a lower incidence of T2DM." (PMID 32685510, 2020). "However, obesity is associated with high circulating leptin levels occurring concomitantly with leptin resistance at the level of the central nervous system." (PMID 32846917, 2020). "In this regard, the development of experimental models of obesity, including diet-induced models as well as the genetic models (i.e. leptin-deficient model) allowed to better understand the role of adenosine system in the pathophysiological mechanisms underlying obesity." (PMID 33536924, 2020). "Leptin deficiency causes over-eating and spontaneous obesity." (PMID 32164196, 2020). "For example, obesity could cause ovulatory dysfunction, sex hormone disorders, and metabolic syndrome by increasing secretion of estrogen and leptin, and decreasing levels of gonadotropins and progestin." (PMID 32324768, 2020). "This exploratory analysis points toward the possibility that the role of leptin in frailty pathogenesis may be mediated through obesity‐associated pathways." (PMID 32762010, 2020). "There are many proposed mechanisms for the association of obesity with hypertension with one of the major hypotheses involving the effect of leptin on sympathetic neural activation." (PMID 32395338, 2020). "Thus, on the basis of the pathophysiology underlying obesity, alleviation of leptin resistance is a reasonable and long-awaited therapeutic strategy for treating obesity, the anticipated outcome of which would be normalization of energy metabolism regulation." (PMID 32670063, 2020). "These genomic loci are located in proximity to obesity-associated genes such as LEP." (PMID 32967728, 2020). "In rodents, high-fat intake may be associated with increased serum leptin and obesity, and these leptin levels are related to the body lipid content." (PMID 31937343, 2020). "The reduction of the leptin level could indicate the resolution of leptin resistance accompanied with bodyweight reduction because overweight or obesity is associated with leptin resistance." (PMID 32656265, 2020). "Thus, the slow excitotoxicity shown in Alzheimer’s disease due to overexcitation of NMDA receptors by glutamate can be linked to obesity through leptin resistance as a risk factor for neurological disorders." (PMID 33312720, 2020). "Leptin positively correlates with adipose storage and nutritional state and plays an important role in energy balance and appetite control and is also known as a potential mediator of obesity-associated cancers." (PMID 33381605, 2020). "Taken together, the signaling interaction between leptin and IFNγ, particularly in adipose tissue of obese individuals, may play a key modulating role in obesity-associated metabolic disorders and development of pathology." (PMID 33379198, 2020). "Obesity-associated enlargement of adipocytes in humans results in accelerated secretion of leptin and therefore higher serum leptin levels, which may also result from chronic hyperinsulinemia and increased cortisol turnover." (PMID 32655492, 2020). "Elevated leptin levels can also cause obesity, diabetes, and heart disease." (PMID 32397260, 2020). "However, studies of the relationships between leptin levels and cardiovascular risk have mainly performed on DM or obesity patients." (PMID 32403968, 2020).
Obesity (continued). "Obesity is also associated with the production of several adipocytokines hypothesized to promote oncogenesis, including leptin, tumor necrosis factor-alpha (TNFα), interleukin-6 (IL-6), IL-7, and IL-8." (PMID 33105727, 2020). "How increased levels of body fat and obesity, that are frequently associated with alterations in insulin and leptin dependent signaling, influence these signaling networks in the context of melanoma progression is unknown." (PMID 32549336, 2020). "Additionally, hypoxia, a condition that has been associated with both obesity and leptin, increases CXCR4 expression on monocytes and macrophages, thereby inducing TAM trafficking and retention into the low oxygen tension tumor areas." (PMID 32260113, 2020). "Among them, the highest BMI at all time points was observed in the rapid-rising group, indicating that an elevation of leptin level in childhood could be a risk factor for obesity development in the near future." (PMID 33114326, 2020). "Although these are mainly cross-sectional studies covering different childhood periods and phenotypes, they showed that whole blood DNAm levels within the leptin gene promoter boundaries were associated with BMI in infancy, along with obesity and insulin resistance in later life." (PMID 31947745, 2020). "Mice with mutations in either the leptin gene or in the gene encoding the leptin receptor might develop severe obesity and high glucose levels." (PMID 32024487, 2020). "On the contrary, recent findings from two mouse models of reduced leptin expression exposed to high-fat diet suggest that lower levels of leptin during the progression of obesity are protective against weight gain as well as the associated metabolic dysfunction." (PMID 33292104, 2020). "As higher body fat is proportional to higher serum leptin levels, previous findings demonstrating inverse associations between milk intake and obesity in children may partly be explained in light of our findings." (PMID 33036196, 2020). "The ob/ob leptin-deficient mouse is a commonly used murine model for diabetes and obesity." (PMID 32093016, 2020). "Furthermore, the role of leptin is supported by hyperphagia and obesity in db/db mice with mutation in leptin." (PMID 32272767, 2020). "Leptin resistance is highly linked to metabolic dysregulation and obesity." (PMID 32316577, 2020). "Other obesity‐associated factors such as leptin might have been better proxy measures of maternal obesity, since leptin can inhibit inflammation‐mediated MMP2 and MMP9 activation at least at term of pregnancy." (PMID 32614494, 2020). "The disruption of the Hmga2 gene caused a dramatic reduction in obesity of the leptin-deficient mice (Lepob/Lepob) in a gene-dosage-dependent manner: Hmga2+/+ Lepob/Lepob mice weighed over three times more than Hmga2-/- Lepob/Lepob animals, and the weight of Hmga2+/- Lepob/Lepob mice was in between." (PMID 32466162, 2020). "Thus, AC effectively reduced obesity caused by leptin-deficiency and can potentially be used as a nutraceutical for treating obesity." (PMID 32164196, 2020). "Therefore, the in vivo effect of ZAG was studied in ob/ob mice, which are deficient in the hormone leptin and consequently suffer from obesity, hyperphagy and insulin resistance." (PMID 32315567, 2020). "Leptin may act synergistically with other factors that are associated with obesity, such as hyperglycemia, inflammation, and oxidative stress, to accelerate development and progression of cardiovascular diseases." (PMID 32655492, 2020). "Moreover, elevated leptin levels with obesity are likely also a result of leptin resistance, causing its overproduction." (PMID 33362710, 2020). "Therefore, the possible role of adipokines, such as leptin, in the promotion of tumor evolution due to a chronic inflammatory state is also plausible because of the strong association between obesity, inflammation, and HCC." (PMID 33316927, 2020).
Obesity (continued). "Overweight and obesity have been associated with inflammation, oxidative stress, and insulin resistance, as well as with changes in the levels of various bioactive compounds, e.g., lipids, insulin, leptin, adipokines, and some cytokines." (PMID 32599847, 2020). "Leptin is a protein encoded by the gene responsible for obesity." (PMID 33086592, 2020). "Importantly, obesity and excess of adipose tissue result in higher leptin levels and increase the risk of many tumors including skin tumors, melanoma, and non-pigment tumors." (PMID 33008429, 2020). "This suggests that some obesity‐associated maternal factors (including elevated leptin) may differently affect the functions of the placentas of male and female foetuses." (PMID 31703240, 2020). "Another possible explanation for the association between toothbrushing and obesity may be related to leptin, which regulates appetite and energy balance primarily through hypothalamic neurons in the central nervous system." (PMID 32009102, 2020). "Also, sleep loss elevates the level of ghrelin and reduces the level of leptin, which increase appetite and further cause obesity." (PMID 32041532, 2020). "Furthermore, serum leptin in middle-aged men was also strongly linked with obesity-independent insulin resistance and glucose intolerance, which are the risk factors that exacerbate metabolic syndrome." (PMID 33114326, 2020). "Additionally, the methylation of the leptin gene has been observed in different models of animal obesity, reinforcing the idea of the association between leptin methylation and the development of obesity." (PMID 32407841, 2020). "Therefore, disrupted CNS leptin signaling is directly implicated in the development of metabolic diseases, such as hypertension, obesity, and type 2 diabetes." (PMID 33114326, 2020). "One of the explainable mechanisms by which abnormal sleep patterns are associated with increased appetite and dietary consumption is by reducing circulating leptin and elevating ghrelin, which may lead to an increased risk of obesity." (PMID 32645989, 2020). "On the other hand, obesity-associated inflammatory processes with increased production of leptin and cytokines may trigger bronchial inflammation with the appearance of asthmatic symptoms." (PMID 33134805, 2020). "The levels of circulating and/or locally produced leptin might be determinant for the initiation and maintenance of dysmetabolic states associated with obesity." (PMID 32756352, 2020). "The increased LEPR expression observed in the Obese group suggests that the receptor plays a modulating role in the skin system control and that serum LEP may have a role in the pathogenesis of skin disease associated with obesity." (PMID 33316917, 2020). "Given the strong positive association between high leptin levels and body mass index (BMI) and body fat mass, leptin may mediate the link between the increased risk of pregnancy complications in women with obesity." (PMID 32313676, 2020). "Meanwhile, diabetes associated with obesity leads to an unbalanced physiology of the leptin system." (PMID 32816039, 2020). "In addition—and similar to obesity—AT paucity causes dysregulation of several endocrine adipocyte-derived factors, e.g., leptin and adiponectin, which are critical for the adequate regulation of glucose metabolism and energy homeostasis." (PMID 33003626, 2020). "Furthermore, considering that adipokines, especially leptin and adiponectin have potential roles in the pathogenesis of obesity, evaluation of association between these adipokines with two studied lncRNAs is suggested." (PMID 32368256, 2020). "Aged rats were reported to develop leptin resistance that is typically associated with obesity." (PMID 32825115, 2020). "The most common forms of obesity are associated with leptin resistance (a process similar to insulin resistance in type 2 diabetes), which mitigates its anorexigenic effect and consequently inhibits nutrition, despite the high circulating leptin." (PMID 32545890, 2020).